ARID1A (AT-rich interaction domain 1A)
Diseases named in the same sentence as ARID1A in open-access papers (continued):
Sharing a sentence is not in itself a finding about the gene and the disease.
cancer (continued). "Genetic deregulation of ConsensusDriver ERGs often co-occurred in the same sample across several cancer types, with KMT2D and ARID1A having the highest co-occurrence scores." (PMID 32963031, 2020). "Although ARID1A alterations were correlated with significantly inferior OS in total populations, they were associated with significantly prolonged OS in ICI treatment cohort, suggesting it might be used to predict a survival benefit from ICI therapy across multiple cancer types." (PMID 31949479, 2020). "Then, several retrospective and exploratory studies reported the relationship between ARID1A alterations and clinical benefit to ICI in some cancers." (PMID 31949479, 2020). "In comparison, ARID1A was the ERG with the most frequent driver score, appearing in 13 cancer types, although with a relatively weak to modest driver role in individual cancer categories." (PMID 32963031, 2020). "It was uncovered that PTEN, ARID1A, PIK3R1 and ZFHX3 were important suppressors that participated in cancer development." (PMID 32699528, 2020). "Further overlap of these genes with those downregulated following ARID1A deletion in HCT116 cells yielded 317 potential direct enhancer targets, including several interesting cancer-relevant genes." (PMID 31217031, 2019). "Similar to the ARID1A/ARID1B functional dependency, SMARCA4 mutant cancer cells showed sensitivity to SMARCA2 depletion." (PMID 31769422, 2019). "We also compared the genes identified for LUAD and LUSC and found only five genes (ARID1A, CDKN2A, EGFR, MLL3, and RB1) are common for the two cancer types, demonstrating their different disease mechanism." (PMID 30828525, 2019). "ARID1A and ARID1B are mutually exclusive, and few studies have been done to characterize the functional dependency between ARID1A and ARID1B in cancer." (PMID 31769422, 2019). "Arid1a is part of the SWI/SNF chromatin remodeling complex and has an antagonistic relationship with Ezh2 of the PRC2 complex in cancer development." (PMID 31259687, 2019). "ARID1A, a subunit enabling sequence-unspecific DNA-binding of BAF complexes, is the most commonly altered SWI/SNF subunit across all human cancers and a potential tumor suppressor protein." (PMID 30138427, 2018). "Interestingly, ARID1A mutations are not sufficient on their own to cause cancer." (PMID 29456620, 2018). "Recurrent mutations were identified in chromatin regulators and particularly ARID1A and ARID2 in HCCs and PDAs and in the TERT and TERT promoter locus in all kinds of HBP cancers." (PMID 28106782, 2017). "Studies looking into vulnerabilities of ARID1A and BRG1 mutant cancers have proposed to target residual SWI/SNF complexes in what has been termed “cancer-selective paralog dependency”." (PMID 27737960, 2016). "A further large-scale mutation of interest was identified from a split read in the Complete Genomics data between chr1:27,080,702 (intron 16 of ARID1A) and chr1: 109,834,252 (close to MYBPHL) in cancer P13." (PMID 25790038, 2015). "In addition to BRG1 and BRM, functional redundancy may exist among other subunits (e.g., BAF60A, BAF60B, and BAF60C; or BAF155 and BAF170; or ARID1A and ARID1B), which suggests a mechanism by which the SWI/SNF complex may be further protected from cancer-driven subunit loss." (PMID 25774356, 2014).
cancer (continued). "The mutations in the genes that have regulatory roles in gene expression have been reported in lung and other cancers, such as chromatin remodeling factors (e.g. ARID1A/BAF250A and SMARCA4/BRG1) and splicing factors (e.g. U2AF1 and RBM10)." (PMID 25378332, 2014). "In this study, we demonstrate that depletion of ARID1A protein expression significantly increases the sensitivity of cancer cells towards PI3K- and AKT-inhibitors, which is reflected by increased rates of apoptosis in treated ARID1A-depleted cells." (PMID 24979463, 2014). "ARID1A, a subunit of the SWI/SNF chromatin-remodeling complex, plays a critical role in maintaining genomic stability and regulating estrogen receptor (ER) signaling, yet its phosphorylation dynamics in cancer remain underexplored." (PMID 41572083, 2026). "Outside of the EGFR comutation context, the opposite has been observed, with several studies reporting an association between ARID1A alterations and longer PFS and OS following treatment with ICI, not just in NSCLC but across a range of cancers." (PMID 41387924, 2025). "Targeting KLF5 in ARID1A-deficient cancer cells has a negative CRISPR score, which indicates ARID1A mutant cells are sensitive to KLF5 depletion." (PMID 39779698, 2025). "Given that ARID1A sustains cell proliferation in response to DNA damage and cancer cells lacking ARID1A are potentially vulnerable to cisplatin, we next tried to unravel potential clinical significance of KMT2D in management of HCC." (PMID 39564571, 2024). "ARID1A-deficient cancers are dependent on the non-catalytic role of the zeste 2 polycomb repressive complex 2 subunit (EZH2), promising therapeutic utility for ARID1A-deficient tumors." (PMID 38922524, 2024). "In some respects, MSS-GS cancers resembled MSI cancers with respect to proximal location, near-diploid genomes and shared driver genes such as TGFBR2, ACVR2A and ARID1A, but there was no increased mutation burden." (PMID 39112709, 2024). "Conversely, restoration of ARID1A rescued MMR and reduced cancer cell mutability." (PMID 38275587, 2023). "To illustrate the context-dependency of synthetic lethality, we further analyzed the cell type dependencies on ARID1B in cancers with or without ARID1A-deficinecy across 32 cancer types." (PMID 36980292, 2023). "The combination of these targeted therapies with immune checkpoint inhibitors (ICIs) shows potential for producing synergistic effects in the treatment of cancers lacking ARID1A." (PMID 38041544, 2023). "Multivariate logistic regression showed that the amount of pAKT-Thr308 was significantly elevated in carcinomas lacking BAF250a (ARID1A) immunohistochemical expression." (PMID 37627318, 2023). "Mutations in MAATP53, EGFR, FAT4, KMT2C, ARID1A, FAT1, and RNF213 were observed in the original cancer tissues, whereas KRAS and BRAF mutations were not identified." (PMID 35721089, 2022). "Additionally, sufficient studies have suggested that SETD2, BAP1, mTOR, MUC16, HMCN1, KDM5C, ARID1A, and PTEN are intimately tied to prognosis and immune response in cancers." (PMID 35936012, 2022). "Using CRISPR-Cas9 gene editing, the ARID1A was deleted from 786-0 and PANC1 cancer cells." (PMID 35393414, 2022). "Blood biopsies with versus without functional ARID1A alterations also more frequently harbored alterations in ≥1 gene in many important cancer-related pathways, such as signal transduction, RAS/RAF/MAPK, PI3K/Akt/mTor, and the cell cycle." (PMID 36077815, 2022). "It’s reported that ARID1A depletion accelerates EMT, increases cancer stemness and promotes migration, invasion and angiogenesis in various cancers by reducing the chromatin accessibility of target genes or influencing the post-transcriptional modification process." (PMID 36329699, 2022).
cancer (continued). "Recurrent somatic mutations in chromatin remodeling-related genes have been detected with high frequency in human cancers, and three of them, including KMT2D, ARID1A and KMT2C, were the third, fifth and seventh-most commonly mutated cancer genes in a pan-cancer cohort containing around 33,000 cases." (PMID 35681795, 2022). "KRAS, ARID1A, and PIK3CA are three genes, which are frequently muted in human cancers worldwide." (PMID 36072979, 2022). "In fact, association between ARID1A mutation and favorable ICB treatment outcome in other cancer types is not scarce." (PMID 36281289, 2022). "Despite previous reports that ARID1a (BAF250) is linked to glucocorticoid resistance and is widely mutated across a multitude of human carcinomas, its precise role in GR signaling has not been well characterized." (PMID 36344675, 2022). "The variation rate of ARID1A in CCA (without distinguishing cancer type), ICC, and ECC was 15–55%, 6.9–68.2%, and 5–55%, respectively." (PMID 34249744, 2021). "Here in this article, DDR and its role in cancer therapy will be briefly reviewed, then we will recapitulate the preclinical studies pointing to the potential of DDR targeting in OCCC treatment, with emphasis on the role of ARID1A in DDR." (PMID 34737943, 2021). "ARID1A-attenuated GC has no characteristic clinicopathologic features, except for a predilection to stump cancer and low HER2 positivity (P < 0.05)." (PMID 33481850, 2021). "We identified somatic variants (VAF ranging from 0.11 to 0.42) involving DNA repair and replication, the SWI/SNF complex (ARID1A), and other cancer-related genes, but none were recurrently altered." (PMID 34261517, 2021). "The BAF subunit ARID1A binds DNA non-specifically via its AT-rich interactive DNA-binding domain and has the highest mutation frequency among BAF subunits in cancer." (PMID 33941852, 2021). "Our results indicated that ARID1A and ARID1B could alter the biological behaviour of CHOL cells through epigenetic regulation of cancer stemness." (PMID 35127746, 2021). "In intramucosal EBVaGC, there were ARID1A-lost (n = 5) and -preserved tumors (n = 7), suggesting that ARID1A-lost carcinomas are derived from ARID1A-lost precursor cells in the non-neoplastic mucosa." (PMID 34469459, 2021). "These facts suggest that EBER-positive glands with lost and preserved ARID1A expression in the non-neoplastic mucosa are direct precursor of ARID1A-lost and ARID1A-preserved carcinomas of EBVaGC, respectively." (PMID 34469459, 2021). "Given the results reported in this research, we proposed that ARID1A and ARID1B might be equally important in cancer immunotherapy and the prognosis of NSCLC." (PMID 32791957, 2020). "In this study, somatic alterations of two cancer-related genes, including the RECQL4 and the JAK3, had significant associations with non-MGC development, and the ARID1A and the MAGI1 genes had significant associations with metachronous development." (PMID 33328548, 2020). "ARID1B, an isoform that is mutually exclusive with ARID1A in the SWI/SNF complexes and that is involved in regulating transcription and multiple downstream cellular processes, has been recently identified to be the primary mutant gene in various cancers." (PMID 32162380, 2020).
cancer (continued). "A very recent study has reported that ARID1A regulates the glutathione metabolism through an increased transcription of SLC7A11, so that the inhibition of glutathione metabolism increases ROS level and induces apoptosis in cancer cells." (PMID 32763516, 2020). "On the other hand, Helming and colleagues found a synthetic lethal relationship of ARID1A and ARID1B in a subgroup but not in all of the analyzed ARID1A mutated cancer cell lines, describing ARID1B as a specific vulnerability in ARID1A-mutant cancers." (PMID 31796878, 2019). "The transcriptome is therefore an attractive subject of research in cancer and other human pathologies, and some of the cancer genes, such as FOXL2 in granulosa-cell tumors and ARID1A in clear cell carcinomas of the ovary, were initially discovered through transcriptome sequencing." (PMID 29267927, 2018). "PARP inhibitors were developed based on the concept that they could lead cancer cells to apoptosis when the cancer cells lack HR enzymes, including BRCA1/2, PTEN, CtIP and ARID1A." (PMID 29152062, 2017). "In this case, cancer cells lacking SMARCA4 or ARID1A, two core components of the SWI/SNF complex, become dependent on the corresponding paralogs, SMARCA2 and ARID1B, respectively." (PMID 28430577, 2017). "Finally, 47.0% and 51.3% of participants with ARID1A− and ARID1A+ had a low grade cancer (p = 0.14)." (PMID 26384299, 2015). "Silencing ARID1B impaired cellular proliferation in cancer cells with ARID1A mutations, but not in cells with wild-type ARID1A, suggesting that ARID1B is a potential therapeutic target for cancers with ARID1A mutation." (PMID 26384299, 2015). "In addition, we found five genes with CNA losses (DMD, ARID1A, RB1, RAD51B and PTEN) that overlapped pan-cancer CNA drivers." (PMID 26429873, 2015). "Our study reveals a biochemical function of ARID1A/ARID1B in BAF-mediated chromatin remodeling, suggesting a model in which dysregulation of histone octamer transfer activity of BAF complexes may be relevant to cancer formation." (PMID 41017120, 2025). "The depletion of ARID1A and ARID1B leads to a reduction in the accessibility of AP‐1 binding sites, a decrease in the distance between nucleosomes, and affects the binding of AP‐1 transcription factors, thereby influencing the expression of multiple cancer‐related genes, including MET." (PMID 39779467, 2025). "Our study reveals a biochemical function of ARID1A/ARID1B in BAF-mediated chromatin remodeling, suggesting a model in which dysregulation of histone octamer transfer activity of BAF complexes may lead to cancer formation." (PMID 41017120, 2025). "Therefore, increasing ARID1A levels and SWI/SNF complex activity in normal breast epithelium may be beneficial in inhibiting the formation of cancer cells." (PMID 38365747, 2024). "The absence of ARID1A may render cancer cells more sensitive to PARP inhibition through specific pathways." (PMID 38365747, 2024). "However, the efficacy of PARP inhibitor monotherapy in cancers lacking ARID1A is somewhat limited, often requiring combination therapy for enhanced effectiveness." (PMID 38893181, 2024).
cancer (continued). "A variety of compounds are being tested in ARID1A+ cancers, without any drug approval so far." (PMID 37711591, 2023). "Additionally, ARID1A knockout cells spare PARP pathways, and inhibition of PARP, such as Olaparib, Niraparib, Rucaparib, and Veliparib, could accelerate cancer cell death." (PMID 38203635, 2023). "However, the role of ARID1A in cancer is still not fully defined, in fact, some authors suggested a tumor suppression role, while others indicate its oncogenic function." (PMID 36695883, 2023). "In line with context-dependent functions of ARID1A, a recent study in HCC provides additional insights into the link between epigenetic regulatory function of ARID1A to cancer metabolism, which may offer a new possibility of targeting the metabolic vulnerability in certain HCC patients." (PMID 36980292, 2023). "However, PARP inhibitor monotherapy has minimal effect on cancers lacking ARID1A, and it often needs to work in combination with other drugs." (PMID 38008753, 2023). "Thus, in normal breast epithelium, the ability to increase ARID1A levels and increased activity of the SWI/SNF complex may be beneficial for the suppression of cancer cell formation." (PMID 36078038, 2022). "When the grade of luminal formation was scored as 0–3 (0, none; 1, <10%; 2, 10%–50%; and 3, >50% of cancer cell nests), four of five ARID1A-lost EBVaGCs showed grade 2–3, while five of seven ARID1A-preserved tumors showed grade 0–1 (p = 0.0659, Wilcoxon rank sum test)." (PMID 34469459, 2021). "Interestingly, as a consequence of deficient ARID1A protein, the SLC7A11 cystine/glutamate antiporter is not transcribed, and these cancer cells consequently lack robust levels of intracellular cystine." (PMID 31434226, 2019). "Furthermore, based on our analysis of DepMap data, targeting KLF4 in ARID1A-deficient cancer cells does not appear to influence the fitness of ARID1A mutant cell lines, further highlighting the specificity of the effect of loss of KLF5 on ARID1A -deficient cells." (PMID 39779698, 2025). "Another plausible explanation for the poor prognosis of ARID1A‐negative patients is that ARID1A negativity induced the suppression of critical genes responsible for chemotherapy and radiotherapy sensitivity, leading to radioresistance or chemoresistance of cancer cells." (PMID 37366273, 2023). "Genetically engineered mouse models have shown that the combinations with Pten ablation with mutations of Pik3ca, Arid1a, or KrasG12D promote and aggressively develop invasive endometrial carcinomas, whereas solely PTEN loss does not or takes a long time to induce malignant tumors." (PMID 35203298, 2022). "However, many genes listed in the Cancer Gene Census as known driver genes were affected by nonsilent mutations, including genes that are frequently mutated in Western UTUC patients 11,12, such as KMT2A, C and D (27%) and ARID1A (14%)." (PMID 32292497, 2020). "Importantly, patients with ARID1A alterations and advanced cancers had the substantially prolonged overall survival in ICI treatment cohort, suggesting it might be used to predict a survival benefit from ICI therapy across multiple cancer types." (PMID 31949479, 2020).